SYP (synaptophysin)
Diseases named in the same sentence as SYP in open-access papers (continued):
Sharing a sentence is not in itself a finding about the gene and the disease.
paraganglioma (31 papers, 2005 to 2025). A benign or malignant neoplasm arising from paraganglia located along the sympathetic or parasympathetic nerves. "Immunohistochemistry confirmed the tumor's chromaffin nature, with chief cells testing positive for CD56, Synaptophysin, and Chromogranin A, and sustentacular cells positive for S100 protein, consistent with a diagnosis of paraganglioma." (PMID 40197392, 2025). "SYP has been connected to diabetic islet cell tumors, paragangliomas, and thyroid medullary carcinomas." (PMID 39314560, 2024). "In a similar vein, once SYP was discovered to be a vesicle protein (presynaptic) in a variety of nervous tissue, SYP expression was discovered in pancreatic islet cells, NETs, pheochromocytomas, and paragangliomas." (PMID 39314560, 2024). "Paragangliomas often express chromophobic proteins, synaptophysin, neuron-specific enolase, CD56 and supporting cell S100 protein." (PMID 38013330, 2023). "A common aspect of paraganglioma culture is the formation of cell agglomerations or masses that appear initially to include many synaptophysin and tyrosine hydroxylase-positive cells but quickly lose these cells or cells lose expression of these markers." (PMID 36178902, 2022). "Studies have shown that most paragangliomas are S100 positive, synaptophysin (+), pheochromogranin(+), vimentin(+), and AE1 + AE3 negative." (PMID 36581844, 2022). "On a similar note, following the identification of SYP as a presynaptic vesicle protein in various neuronal tissues, succeeding studies identified SYP expression in pheochromocytoma and paraganglioma as well as in pancreatic islet cells and NETs." (PMID 34571751, 2021). "Immunohistochemical examination confirmed paraganglioma with the classic zellballen appearance which stained positive for chromogranin, synaptophysin, and S-100 in the periphery." (PMID 32685227, 2020). "Paraganglioma exhibit positivity to neural markers such as Synaptophysin, Chromogranin, S-100 with low cytokeratin expression." (PMID 30952024, 2019). "Apart from central necrosis, vascular and lymphatic invasion and mitotic abnormalities; chromogranin A, vimentin, S-100, synaptophysin can be used in the immunohistochemical analysis of paragangliomas and indicate the true nature of the tumour." (PMID 29255564, 2017). "The resected tumor was diagnosed as the ACTH-secreting paraganglioma in the pathological examination, which was confirmed by immunohistochemical studies with chromogranin A, synaptophysin, and ACTH." (PMID 28225994, 2017). "Paragangliomas will show positivity for synaptophysin, chromogramin, and S100 protein stains in sustenticular cells with negativity for PTH." (PMID 28003924, 2016). "Immunohistochemical staining was positive for synaptophysin and chromogranin A. Based on these findings, the resected tumors were histopathologically diagnosed with liver metastases from the retroperitoneal paraganglioma." (PMID 26943413, 2015). "Both Chromogranin A and synaptophysin were strongly and diffusely positive in the pheochromocytoma/paraganglioma cells." (PMID 23587063, 2013). "Paragangliomas stain substantially positive for chromogranin A and synaptophysin and exclusively positive for S-100 proteins, while gastrointestinal glomus tumors barely stain positive for S-100 proteins." (PMID 23691399, 2013). "Chromogranin A and synaptophysin are the most common neuropeptides synthesized in endocrine cells and can be used for immunohistochemical analysis of paragangliomas along with other protein markers such as neuron specific enolase and vimentin." (PMID 23537060, 2013). "Pathology of the bilateral masses excised confirmed evidence of paraganglioma with immunohistochemical stains showing neoplastic cells positive for synaptophysin, chromogranin (weak), and S100 (around sustentacular cells), supporting the diagnosis of paraganglioma." (PMID 39070388, 2024).
paraganglioma (continued). "Synaptophysin-positive cells from tumour 44 (a thoracic paraganglioma carrying the SDHD Dutch founder variant p.Asp92Tyr) were noticeably more persistent in cultures with higher lactate levels." (PMID 36178902, 2022). "However, paraganglioma cells are positive for chromogranin and synaptophysin, and at least focally they are arranged in characteristic nests." (PMID 22472343, 2012). "Paraganglioma may show alveolar structures as well, but, in contrast, is positive by immunohistochemistry for chromogranin and synaptophysin (neuroendocrine markers) and lacks crystalline cytoplasmatic inclusions." (PMID 18593459, 2008). "In our case, the histological findings were compatible with malignant paraganglioma, showing a Ki-67 index > 1%, polygonal cells with eosinophilic cytoplasm in a prominent vascular component (the typical Zellballen structures), and lastly positive staining for chromogranin, synaptophysin and CD56." (PMID 24289190, 2013). "A positive staining with synaptophysin, NSE, CD56, NSE, Syn, CgA and S-100 was observed in the present case, which was compatible with paraganglioma." (PMID 24520306, 2014). "Paraganglioma was excluded based on patchy pan-cytokeratin expression, negative synaptophysin, and absence of S100-positive sustentacular cells (not shown)." (PMID 40762649, 2025). "When chromogranin and synaptophysin are negative with these paraganglioma-like features, a positive nuclear B-catenin and a point mutation of CTNNB1 can separate this tumor from radiologic and morphologic cellular and stromal mimickers." (PMID 39093425, 2025). "The reported case here in was unlikely to be a carcinoid tumour and paraganglioma, since tumour cells lack both neuroendocrine marker (chromogranin and SYP) as well as S100." (PMID 34508517, 2021). "Negativity for PAX8 ruled out ccRCC; negativity for chromogramin and synaptophysin ruled out paraganglioma." (PMID 28003924, 2016). "Negative staining for AE1/AE3, EMA and CD10 exclude the probability of RCC; Negative staining for synaptophysin, chromogranin and calretinin exclude the probability of adrenal cortical carcinoma and paraganglioma." (PMID 22548972, 2012). "Although, some of the cytomorphological features overlapped, the tumor cells in this case were non-immunoreactive for neuroendocrine markers such as chromogranin and synaptophysin in cellblock sections without Zellballen arrangement excluding paraganglioma." (PMID 15967023, 2005). "Paragangliomas also display a distinctive nested (zellballen) architecture comprised of neuroendocrine cells and show positive staining for neuroendocrine markers such as synaptophysin and chromogranin, features not observed in PMTs." (PMID 39493128, 2024). "On the other hand, a negative staining for chromogranin or synaptophysin generally excludes the hypothesis of adrenal carcinoma and paraganglioma, which stain positively for these proteins." (PMID 24591762, 2014). "Paraganglioma, but not ASPS, expresses neuroendocrine markers, such as chromogranin A and synaptophysin." (PMID 26369552, 2015).
memory impairment (30 papers, 2013 to 2025). "For example, heat stress-induced memory impairment in the novel object recognition and Y-maze tasks is associated with a decreased level of synaptophysin expression in the hippocampus." (PMID 29132299, 2017). "Memory impairment was associated with decreased hippocampal synaptophysin in a mice model of Alzheimer." (PMID 24655810, 2014). "In the current study, we found that esketamine could prevent synaptic dysfunction and the loss of synapse-associated proteins PSD95 and SYP, which have a close relationship with severe memory impairment and depressive behaviour." (PMID 38221533, 2024). "Decreased expression of PSD-95 and synaptophysin proteins are linked to memory impairment." (PMID 39281480, 2024). "And the depletion of acetate‐producing bacteria caused the reduction of synaptophysin (SYP) in the hippocampus, which resulted in learning and memory impairments." (PMID 38236004, 2024). "LPS injection induces memory impairment via the reduction of synapses, demonstrated by decreased SYP and PSD-95 expressions, as well as reduced co-localized puncta." (PMID 36430493, 2022). "In 6-month-old AppNL-G-F mice, the expression of both PSD95 and SYP was significantly decreased in the cortex and hippocampus, indicating that the synapses of AppNL-G-F mice were significantly impaired, which may be associated with the beginning of behavioral and memory impairments." (PMID 34831483, 2021). "Herein, treatment with DHF was shown to up‐regulate decreased synaptophysin levels and was discovered to improved learning and memory impairments." (PMID 27297627, 2016). "As demonstrated in our results, the CA3-a region showed decreased synaptophysin staining that correlated with the learning and memory impairment found in the novel recognition spatial learning task." (PMID 24655810, 2014). "To investigate the molecular mechanisms involved in HIV-1 Vpr induced memory impairment, we examined hippocampal levels of synaptophysin." (PMID 24655810, 2014). "In addition, it was reported that L. rhamnosus GG intake improved cognitive and memory impairment by increasing the expression of SYP, PSD-95, and BDNF in an ethanol-exposed mouse model." (PMID 40002326, 2025). "Moreover, melatonin reverses Aβ1–42‐induced neurotoxicity and memory impairment by increasing the levels of presynaptic proteins (Synaptophysin and SNAP25) and postsynaptic proteins (PSD95 and SNAP23)." (PMID 39500626, 2024). "Regarding synaptophysin, the reduction of this glycoprotein, which predominates in the synaptic vesicles, has been related to memory impairment In this context, as it has been previously commented, obesity also plays a key role in the correct function of memory interconnecting these three concepts." (PMID 35899125, 2022). "OST-induced increase in SYP protein level in the hippocampus may contribute to the amelioration of memory impairment in OVX mice." (PMID 34025413, 2021). "Further, lack of functional synaptic protein expression, including synaptophysin, is associated with hippocampal‐dependent memory impairment (Schmitt, Tanimoto, Seeliger, Schaeffel, & Leube, 2009)." (PMID 31693798, 2020). "The results revealed that BPS induced memory impairment and anxiety in offspring mice, accompanied by abnormal expression levels of brain neurotrophic factor and synaptic plasticity factor (PSD95, SYP)." (PMID 41465379, 2025). "Long-term acetate deficiency due to depletion of acetate-producing bacteria resulted in the reduction of synaptophysin (SYP) in the hippocampus as well as learning and memory impairments." (PMID 34172092, 2021). "The changed hippocampal synaptic protein GAP-43, SYP, PSD-95 levels, serum corticosterone levels, and neuroinflammation were found in sleeping deprivation related memory impairment mice." (PMID 35126189, 2021). "Pre- or postischemia administration of rosmarinic acid alleviated brain injury and memory impairment in MCAO animal models through the modulation of Nrf2, HO-1 and synaptophysin." (PMID 33383852, 2020).
memory impairment (continued). "The ETS-induced decrease in BDNF levels in infancy is consistent with the reductions in the synapsin, synaptophysin and PSD95 protein levels, as well as the learning and memory impairments observed at this age." (PMID 26305213, 2015).
prostate carcinoma (30 papers, 2012 to 2026). A carcinoma that arises from epithelial cells of the prostate gland. "The genotypic characteristics of this prostate cancer variant are highly variable and also show the expression of genes that are used as markers for neuroendocrine (NE) differentiation, e.g., synaptophysin (SYP), chromogranin A (CgA), and enolase 2 (ENO2)." (PMID 35741197, 2022). "Our study presents data from multiple prostate cancer patients, demonstrating the CoDuCo assay’s ability to visualize diverse resistance mechanisms, such as neuroendocrine differentiation markers (SYP, CHGA, NCAM1) and AR-V7 expression." (PMID 39550585, 2024). "To provide additional evidence for the existence of AR and NE double-positive cells, we performed multiplex fluorescence staining and observed the co-localization of AR and SYP in the same prostate cancer cells." (PMID 36033483, 2022). "To extend the potentially clinically relevant cellular readout beyond counts alone, we also stained CTCs for two prostate cancer-relevant markers that imply treatment resistance to ARSIs: Arv7 and SYP." (PMID 35269713, 2022). "These NLS genes positively correlate with conventional neuroendocrine markers such as chromogranin and synaptophysin, and negatively correlate with AR and AR target genes in advanced prostate cancer." (PMID 36159187, 2022). "SYP is a classical neuroendocrine marker, that is expressed in neuroendocrine prostate cancer, an aggressive subtype of prostate cancer." (PMID 35269713, 2022). "Other groups also found a co-localization area of AR and NE markers, especially SYP in hormone-treated prostate cancer samples." (PMID 36033483, 2022). "Cyclooxygenase-2 inhibition increases expression of synaptophysin in metastatic prostate cancer cells." (PMID 29132299, 2017). "A previous study indicates that cyclooxygenase-2 inhibition modulates synaptophysin expression in metastatic prostatic cancer cells." (PMID 29132299, 2017). "In silico analysis of FYN expression in prostate cancer cell line databases revealed an association with the expression of neuroendocrine (NE) markers such as CHGA, CD44, CD56, and SYP." (PMID 26624980, 2015). "To clarify the role of NE differentiation of prostate cancer as it relates to body weight we measured synaptophysin protein expression of the autochthonous tumors." (PMID 23304522, 2012). "Broadly termed aggressive variant prostate cancer (AVPC), these tumors harbor neuroendocrine features and often display small cell histologic properties, which widely involve up-regulation of synaptophysin and chromogranin, high proliferation indices, and a low cytoplasm-to-nuclear ratio." (PMID 41542660, 2026). "Interestingly, in our cohort, Arv7- and SYP-positive CTCs appear to be mutually exclusive, likely representing two independent strategies employed by prostate cancer cells to achieve resistance to ARSI." (PMID 35269713, 2022). "The lack of expression of the prostate-specific genes (AR, NKX3.1, and PSA) at the protein level prompted the investigation of a possible NE prostate cancer phenotype, which was confirmed at the RNA-seq level when 2 NE specific marker (SYP and ENO2) were expressed at RNA-seq." (PMID 36643868, 2022). "We then reviewed 8,194 prostate cancer cases with available immunohistochemistry reports and found 2.3% cases (n = 189) that showed at least one of the NE markers (chromogranin A, synaptophysin, and neural cell adhesion molecule 1) being positive in at least 5% of epithelial cells." (PMID 36033483, 2022). "Neuroendocrine cells do not express AR or PSA, but have markers such as chromogranin A, synaptophysin (SYP), and neuron-specific enolase (NSE) that give NED prostate cancer a distinct biomarker profile and should cause suspicion in cases of metastatic CRPC with low serum PSA." (PMID 29562686, 2018).
prostate carcinoma (continued). "Here, we demonstrated that TNFAIP8 expression induced expression of the NED biomarkers chromogranin A and synaptophysin in prostate cancer cells; however, the exact mechanism by which TNFAIP8 induces NED in prostate cancer cells remains unclear." (PMID 29928491, 2018). "Interestingly, PEG10 overexpression also correlated with expression of chromogranin A and synaptophysin, markers for neuroendocrine prostate cancer, a type of treatment-resistant prostate cancer." (PMID 29245927, 2017). "HCC also hosts VAChT+, synaptophysin+, CD45- and CD31- cells, also nucleated (consistently with NeuN staining), as in prostate cancer with muscarinic signaling." (PMID 39717507, 2025). "Despite seven of nine expressed NE genes, the absence of the benchmark NE markers such as chromogranin and SYP begs for further interrogation into the possible NE phenotype of ACRJ-PC28 and validates the need for diverse prostate cancer cell lines." (PMID 36643868, 2022). "We retrospectively reviewed all 8,194 prostate cancer cases with available immunohistochemistry reports and found 2.3% (n = 189) with any one of the NE markers (CHGA, SYP, and NCAM1) being positive in at least 5% of epithelial cells." (PMID 36033483, 2022). "The expression of common prostate cancer biomarkers, including AR, AMACR, PSA, PSMA, ERG, and neuroendocrine markers (synaptophysin, chromogranin A and CD56) were continually assessed across PDX generations." (PMID 34413304, 2021). "We transiently expressed ID2 in a panel of prostate cancer cell lines; Western blot analysis showed decreased expression of AR and PSA in LNCAP cells, while the expression of NE markers such as CHGA, ENO2, and SYP was elevated in both LNCAP and PC3 cells." (PMID 38254880, 2024). "Therefore, we examined the impact of ELAVL3 overexpression in prostate cancer cell lines and discovered that it effectively stimulated the expression of neuroendocrine markers, alongside MYCN, NCAM1, and SYP when compared with vector control." (PMID 38016952, 2023). "Compared with the other subtypes of prostate cancer, NEPC expresses specific neuroendocrine markers including synaptophysin (SYP), chromogranin A (CgA), and neuronal‐specific enolase (NSE), with concurrent absence of androgen receptor (AR) and prostate‐specific antigen (PSA)." (PMID 33009820, 2021). "Prostate cancer with neuroendocrine differentiation is typically defined by the heterogeneous histological expression of several NE markers in at least 5% of epithelial cells, including chromogranin A (CHGA), synaptophysin (SYP), neural cell adhesion molecule 1 (NCAM1), and enolase 2 (ENO2)." (PMID 36033483, 2022). "We observed that most tumor cells in PIN and prostatic carcinoma/adenocarcinoma lesions expressed E-cadherin and were CK8 positive, but did not express synaptophysin." (PMID 23308230, 2013). "Biopsy-confirmed metastatic lesions in the bladder, rectum, and bone were observed with a pathologic diagnosis of prostate cancer with small cell features, which was supported by negative PSA, positive synaptophysin (SYP) and positive chromogranin (CHGA) on biopsy tissue immunohistochemistry (IHC)." (PMID 41542660, 2026).